TSC2 (TSC complex subunit 2)
Diseases named in the same sentence as TSC2 in open-access papers (continued):
Sharing a sentence is not in itself a finding about the gene and the disease.
neurodevelopmental disorder (15 papers, 2016 to 2026). A behavioral and cognitive disorder with onset during the developmental period that involves impaired or aberrant development of intellectual, motor, or social functions. "Tuberous sclerosis complex (TSC) is a neurodevelopmental disorder with epileptic seizures caused by genetic mutations in either TSC1 or TSC2 gene." (PMID 41484896, 2026). "Tuberous Sclerosis Complex (TSC) is a neurodevelopmental disorder caused by mutations in the TSC1 or TSC2 genes, which encode proteins that negatively regulate mTOR complex 1 (mTORC1) signaling." (PMID 35945201, 2022). "Tuberous Sclerosis Complex (TSC) is a neurodevelopmental disorder caused by mutations in the TSC1 or TSC2 genes, which negatively regulate mTORC1 signalling." (PMID 31780742, 2019). "Tuberous Sclerosis Complex (TSC) is a neurodevelopmental disorder caused by mutations in TSC1 or TSC2, which encode proteins that negatively regulate mTOR complex 1 (mTORC1)." (PMID 31780742, 2019). "mTORC1 inhibition with rapamycin rescued several behavioral phenotypes in Tsc2+/− mice and in other models of neurodevelopmental disorders." (PMID 37293130, 2023). "Tuberous sclerosis complex (TSC) is a neurodevelopmental disorder caused by mutations in the TSC1 and TSC2 genes and autosomal dominantly inherited." (PMID 35241183, 2022). "Tuberous Sclerosis Complex (TSC) is a neurodevelopmental disorder arising primarily from mutations in TSC1 (hamartin) and TSC2 (tuberin) (TSC1/2)." (PMID 35241183, 2022). "Tuberous sclerosis complex (TSC) is a neurodevelopmental disorder, caused by mutations in the TSC1 or TSC2 genes, that is characterized by tumors in multiple organs." (PMID 31761686, 2019). "Tuberous sclerosis complex (TSC), a heritable neurodevelopmental disorder, is caused by mutations in the TSC1 or TSC2 genes." (PMID 30190613, 2018). "Since neurodevelopmental disorders such as ASD are often associated with WM defects, we next aimed to investigate whether Tsc2+/− mice exhibited weak connectivity between important brain regions involved in social behavior." (PMID 38296969, 2024). "Thus, we demonstrate that reduction of Nlgn1 expression in Tsc2+/− mice is a new therapeutic strategy for TSC and potentially other neurodevelopmental disorders." (PMID 37293130, 2023).
kidney disease (12 papers, 2007 to 2024). "The LOD score peak included the Tuberous sclerosis 2 (Tsc2) gene which has already been implicated in kidney disease: loss of function by germline retroviral insertion is associated with spontaneous renal tumorigenesis in the Eker rat, and heterozygous-null Tsc2(+/-) mice develop renal cystadenomas." (PMID 24148528, 2013). "In summary, we have discovered that TFEB plays a fundamental role in the development of kidney disease downstream of Tsc2 knockdown in two distinct mouse models of TSC." (PMID 38195686, 2024). "Nevertheless, some PKD1/TSC2-CGS patients have milder renal disease with mosaicism being the main reason which is rather common in these cases but not supported by the blood derived DNA studies here." (PMID 26077033, 2015). "In order to compare kidney disease severity in different Tsc2+/- mouse strains, we evaluated kidney cystadenomas in cohorts of A/J and C57BL/6 Tsc2+/- mice at nine and twelve months of age." (PMID 20146790, 2010). "From previous studies, we have shown that the severity of kidney disease increases with age in C57BL/6 Tsc2+/- mice." (PMID 20146790, 2010). "The preclinical studies reported here show that the A/J Tsc2+/- mouse model has younger onset TSC related kidney disease and as a result, is an improved mouse model for use in future preclinical studies." (PMID 20146790, 2010). "TSC related kidney disease severity is 5-10 fold higher in A/J Tsc2+/- mice compared with C57BL/6 Tsc2+/- mice." (PMID 20146790, 2010). "We see a 94.5% reduction in kidney disease in Tsc2+/- mice treated with daily rapamycin for one month before and after weekly rapamycin for five months in this study." (PMID 19368729, 2009). "As shown, there are few kidney cystadenomas in untreated Tsc2+/- mice at 3 months but they are easily observed at 7 months and the severity of kidney disease increases by 11 months." (PMID 17986349, 2007). "Tsc2+/- mice were used for a seven-arm preclinical study to determine the impact of the timing of treatment for TSC renal disease and to compare treatment with CCI-779 to CCI-779 plus IFN-γ." (PMID 17986349, 2007). "However, a major disadvantage of the Tsc2+/- mouse model in a predominantly C57BL/6 background is that kidney disease develops gradually so preclinical studies can take 12-18 months to complete." (PMID 20146790, 2010). "Based on the findings of this study, the A/J strain Tsc2+/- mice have a 5-10 fold higher disease burden than C57BL/6 strain Tsc2+/- mice and are a superior and higher through-put Tsc2+/- mouse model for preclinical studies relevant to TSC kidney disease and tumors." (PMID 20146790, 2010). "The Tsc2+/- mouse is an excellent mouse model for the study of TSC related kidney disease." (PMID 20146790, 2010). "Two notable predictions in this region are TSC2, which is already known to be related to kidney disease, and FASN, which may be involved in apoptosis." (PMID 18564415, 2008). "The RPL3L gene encodes the 60S ribosomal protein that is located on chromosome (Chr) 16p13.3 near the PKD1 (polycystic kidney disease 1) and TSC2 (TSC complex subunit 2) genes." (PMID 38254943, 2023). "With TSC1 and TSC2 patients combined, the prevalence of organ involvement stood at 70% of patients with a CHD, 88% with an NDD and 63% with renal disorders." (PMID 35440050, 2022). "In our prior preclinical study using Tsc2+/- mice, single agent IFN-γ was administered for 10 months (from age 2 months-12 months) and there was significant reduction in the severity of kidney disease." (PMID 17986349, 2007). "Recently, however, we observed that a short term course of IFN-g treatment in combination with CCI-779 did not significantly reduce kidney disease in Tsc2+/- mice when treatment was used to treat larger tumors." (PMID 19368729, 2009).
kidney disease (continued). "Tsc2+/- mice were used to compare disease severity of kidney disease in two different mouse strains (C57BL/6 and A/J), evaluate the age related progression of kidney disease (in A/J mice), and compare three different dosing schedules of rapamycin (daily, daily plus weekly, and weekly)." (PMID 20146790, 2010).
neurological disorders (9 papers, 2012 to 2021). "This system was employed to inactivate two genes associated with neurological disorder (TSC2 and KCNQ2) and achieved up to 85% efficiency of gene targeting in the differentiated cells." (PMID 27857203, 2016). "Importantly, aberrant expression of TSC1 or TSC2 causes significant neurological disease, and overactivation of mTOR has been linked to the development of neurodegenerative disorders." (PMID 28732515, 2017). "Mutations in either of two tumor suppressor genes, TSC1 or TSC2, cause tuberous sclerosis complex (TSC), a syndrome resulting in benign hamartomatous tumors and neurological disorders." (PMID 23028662, 2012). "Many neurological disorders have been linked with aberrant AKT signaling caused by germline mutations of certain tumor suppressor genes such as phosphatase and tensin homolog (Pten) or tuberous sclerosis proteins 1 and 2 (Tsc2/Tsc1)." (PMID 29494346, 2018). "Mutations or deletions of phosphatase and tensin homolog (PTEN) and the heterodimeric complex of tuberous sclerosis proteins 1 and 2 (TSC1/hamartin, TSC2/tuberin) can dramatically upregulate mTOR signaling and contribute to a class of human neurological diseases characterized as “TORopathies”." (PMID 24672426, 2014).
autosomal dominant disease (5 papers, 2015 to 2022). Autosomal dominant form of disease. "Tuberous sclerosis complex (TSC) is a rare autosomal dominant disease caused by the mutation in the TSC1 gene or TSC2 gene." (PMID 34243823, 2021). "TSC is an autosomal dominant disease that occurs because of abnormalities in the TSC1 or TSC2 tumor suppressor genes." (PMID 25889454, 2015).
kidney (4 papers, 2010 to 2025). "In our Tsc1 and Tsc2 mutant mice, liver and kidney tumors were observed at the age of 12-month-old." (PMID 41238564, 2025).
metabolic disease (4 papers, 2021 to 2025). A congenital disorder (due to inherited enzyme abnormality) or acquired (due to failure of a metabolically important organ) disorder resulting from an abnormal metabolic process. "Moreover, PKA may also inhibit mTORC1 activity by phosphorylating the upstream regulatory factors of mTORC1, Raptor and TSC2, improving various age‐related diseases such as cardiovascular diseases, neurodegenerative diseases and metabolic diseases." (PMID 40638555, 2025).
CNS tumor (3 papers, 2014 to 2023). "Both NFI and TSC2 are tumor suppressor genes associated with autosomal dominant tumor predisposition syndromes that increase the risk for CNS neoplasms in addition to a constellation of other syndromic features." (PMID 37686092, 2023). "Few studies have directly investigated the hypothesis that TSC1 or TSC2 mutations in neural crest stem cells drive the development of non-CNS tumors in TSC, including LAM." (PMID 25505789, 2014). "Experimental approaches to identify the cell of origin in TSC have focused to date almost exclusively on validating the hypothesis that the CNS tumors and behavioral phenotypes are driven by TSC1 or TSC2 mutations in the NSC lineage." (PMID 25505789, 2014). "However, only two of 44 patients with a CNS tumor carried a germline variant (TSC2, NF1), and none of these two patients had a 1st–3rd-degree family member with a CNS tumor." (PMID 33332384, 2020).
colon polyps (2 papers, 2015 to 2020). "In conclusion, we report that TSC2/mTOR signaling regulates intestinal cell differentiation in a Notch-dependent manner, thus providing a better mechanistic understanding of mTOR inhibition and its potential beneficial effects in certain intestinal diseases." (PMID 25654764, 2015).
adenocarcinoma (1 paper, 2014). A common cancer characterized by the presence of malignant glandular cells. "We then wondered whether expression of hamartin, p-mTOR or p-TSC2 was associated with EGFR-mutations since approximately 20% of adenocarcinoma of the lung patients’ specimens reveal EGFR-mutations." (PMID 24593867, 2014).
brain diseases (1 paper, 2020). "Cul4B has been recently identified to play an important role in regulating TSC2 and mTOR signaling in some brain diseases, and it is also able to degrade 4E-BP2 eukaryotic translation initiation factor." (PMID 33384682, 2020).
inflammation (1 paper, 2023). Aberrant reaction of the microcirculation characterized by movement of fluid and leukocytes from the blood into extravascular tissues. "Looking at clinical manifestations, for instance, the CFA stimulation model and IL1RN deficiency/Tsc2 KO models may be more suitable for studying chronic and arthritic subtypes of SJIA, while the repeated TLR-9 model may be preferable for studying lung inflammation." (PMID 36964620, 2023).
myopathy (1 paper, 2021). A disease of the muscle in which the muscle fibers do not function properly. "When LDB3 is mutated, PKCα and TSC2-mTOR mediated homeostasis is impaired, leading to protein aggregation myopathy." (PMID 33742095, 2021). "The LDB3 p.Ala165Val mutation impairs PKCα and TSC2-mTOR mediated homeostasis in this large protein assembly leading to protein aggregation myopathy." (PMID 33742095, 2021).
psychiatric disease (1 paper, 2024). "In this present study, we demonstrated that psychiatric disease-related behaviors in the Tsc2+/− mice, including abnormal cognitive ability and sociability, resulted from disrupted brain circuitries." (PMID 38296969, 2024).
TSC2 also shares sentences with these, for which no sentence is quoted: Rett syndrome (6 papers); tuberous sclerosis 2 (6); anxiety disorder (4); schizophrenia (4); bipolar disorder (3); esophageal squamous cell carcinoma (3); Peutz-Jeghers syndrome (3); Renal insufficiency (3); renal tumor (3); skin cancer (3); urothelial carcinoma (3); cardiac tumors (2); Cerebral ischemia (2); colon (2); Cortical tubers (2); metastatic cancer (2); neurodegenerative disease (2); neuroendocrine tumors (2); neurofibromatosis (2); neurofibromatosis type 1 (2); paraganglioma (2); rectal cancer (2); acinar cell carcinoma (1); adult onset immunodeficiency syndrome (1); agoraphobia (1); alcohol (1); Alport syndrome (1); Angelman syndrome (1); attention deficit-hyperactivity disorder (1); autosomal dominant lateral temporal lobe epilepsy (1).
A further 110 diseases each share a sentence with TSC2 in 1 paper.